HMGB1P46 (high mobility group box 1 pseudogene 46)
Gene: Processed pseudogene on chromosome 8 (107,173,200 to 107,173,809, reverse strand). Ensembl gene ENSG00000254146.
Diseases named in the same sentence as HMGB1P46 in open-access papers:
HMGB1P46 is named in the same sentence as 1 disease in open-access papers, as found by Europe PMC text mining. Sharing a sentence is not in itself a finding about the gene and the disease. The quoted sentences say what the papers report.
diabetes (2 papers, 2015 to 2018). "We have provided genetic evidence that SNPs in Chr1p35.1 (ZSCAN20-TLR12P) and Chr8p23.1 (HMGB1P46) may be involved with neuropathic pain in diabetes." (PMID 26629533, 2015).